MTMR9 (myotubularin related protein 9)
Description:
Acts as an adapter for myotubularin-related phosphatases. Increases lipid phosphatase MTMR6 catalytic activity, specifically towards phosphatidylinositol 3,5-bisphosphate and MTMR6 binding affinity for phosphorylated phosphatidylinositols. Positively regulates lipid phosphatase MTMR7 catalytic activity (By similarity). Increases MTMR8 catalytic activity towards phosphatidylinositol 3-phosphate. The formation of the MTMR6-MTMR9 complex, stabilizes both MTMR6 and MTMR9 protein levels. Stabilizes MTMR8 protein levels. Plays a role in the late stages of macropinocytosis possibly by regulating MTMR6-mediated dephosphorylation of phosphatidylinositol 3-phosphate in membrane ruffles. Negatively regulates autophagy, in part via its association with MTMR8. Negatively regulates DNA damage-induced apoptosis, in part via its association with MTMR6. Does not bind mono-, di- and tri-phosphorylated phosphatidylinositols, phosphatidic acid and phosphatidylserine.
Synonyms: C8orf9; MTMR8; DKFZp434K171; LIP-STYX
Tractability: Antibody: UniProt places it where antibodies can reach, with high confidence; its Gene Ontology location is reachable by antibodies, with medium confidence. PROTAC: ubiquitination databases record sites on it; its protein half-life has been measured.
Gene: Protein-coding gene on chromosome 8 (11,284,523 to 11,328,146, forward strand). Ensembl gene ENSG00000104643.
Subcellular location: Cytoplasm; Cell projection, ruffle membrane; Cytoplasm, perinuclear region; Endoplasmic reticulum
Subcellular location (Human Protein Atlas): Centrosome; Actin filaments
Pathways (Reactome):
Metabolism: Synthesis of IP2, IP, and Ins in the cytosol; Synthesis of PIPs at the late endosome membrane; Synthesis of PIPs at the plasma membrane
Gene Ontology:
Molecular function: phosphatase activator activity; protein binding; protein phosphatase binding; enzyme regulator activity
Biological process: negative regulation of autophagy; positive regulation of phosphatase activity; protein stabilization; regulation of phosphatidylinositol dephosphorylation; phosphatidylinositol biosynthetic process; phosphatidylinositol dephosphorylation
Cellular component: cytoplasm; endoplasmic reticulum; protein-containing complex; cytosol; perinuclear region of cytoplasm; ruffle membrane
Genetic constraint (gnomAD): Loss-of-function variants: 38 observed, 64.56 expected, observed/expected ratio (o/e) 0.59, 90% interval 0.45 to 0.77. The synonymous counts are far from expectation, so gnomAD's model fits this gene poorly and the ratio says little. Missense variants: 841 observed, 652.26 expected, observed/expected ratio (o/e) 1.29, 90% interval 1.22 to 1.37. Synonymous variants: 334 observed, 240.79 expected, observed/expected ratio (o/e) 1.39, 90% interval 1.27 to 1.52.
Homologues: Orthologues: chimpanzee MTMR9 (100% identical), macaque MTMR9 (99% identical), dog MTMR9 (98% identical), rabbit MTMR9 (98% identical), pig MTMR9 (98% identical), rat Mtmr9 (95% identical), mouse Mtmr9 (95% identical), guinea pig MTMR9 (94% identical), tropical clawed frog mtmr9 (84% identical), zebrafish mtmr9 (82% identical), Drosophila melanogaster CG5026 (49% identical), Caenorhabditis elegans mtm-9 (44% identical), and 10 more. Paralogues in human: MTMR7 (34% identical), MTMR2 (33% identical), MTMR1 (32% identical), MTMR6 (32% identical), MTM1 (32% identical), MTMR8 (31% identical), MTMR3 (30% identical), MTMR4 (29% identical), SBF1 (29% identical), SBF2 (27% identical), MTMR10 (25% identical), MTMR11 (25% identical), and 1 more.
Diseases named in the same sentence as MTMR9 in open-access papers:
MTMR9 is named in the same sentence as 15 diseases in open-access papers, as found by Europe PMC text mining. Sharing a sentence is not in itself a finding about the gene and the disease. The quoted sentences say what the papers report.
Obesity (5 papers, 2013 to 2024). Accumulation of substantial excess body fat. "A single nucleotide polymorphism of MTMR9 has been associated with obesity and hypertension." (PMID 36106167, 2022). "Further analysis shows that the transcription level of MTMR9 in the mouse hypothalamic region is increased after fasting while decreased after high-fat diet, suggesting that genetic variants in MTMR9 may cause obesity and hypertension by regulating hypothalamic neuropeptides." (PMID 38529329, 2024). "The transcript level of MTMR9 in the murine hypothalamic region is elevated after fasting and decreased after a high-fat diet, suggesting that MTMR9 may participate in the development of obesity and hypertension by regulating hypothalamic neuropeptides." (PMID 36106167, 2022). "Therefore, MTMR9 provides a candidate target for the development of new drugs for the prevention and treatment of obesity." (PMID 36106167, 2022).
Hypertension (2 papers, 2022 to 2024). The presence of chronic increased pressure in the systemic arterial system. "And the rs752107 polymorphism of WNT3A gene is significantly associated with susceptibility to Essential hypertension (EH), and is also associated with the risk of heart failure (HF) and ischemic stroke (IS), suggesting that MTMR9 may be a target between Wnt signaling and cardiovascular diseases." (PMID 38529329, 2024).
esophageal cancer (1 paper, 2024). A primary or metastatic malignant neoplasm involving the esophagus. "Research has indicated a correlation between high MTMR9 expression and poor outcomes in patients with esophageal cancer." (PMID 39524444, 2024).
oesophageal adenocarcinoma (1 paper, 2014). "Two possible targets of this miRNAs are fibronectin type III domain containing 3A (FNDC3A), whose expression controls cell adhesion, migration and proliferation and myotubularin related protein 9 (MTM9), whose chromosomal gain is considered a prognostic event in oesophageal adenocarcinoma." (PMID 24866763, 2014).
psoriasis (1 paper, 2023). An autoimmune condition characterized by red, well-delineated plaques with silvery scales that are usually on the extensor surfaces and scalp. "We also identified five novel psoriasis risk genes, methionine sulfoxide reductase A, elongation factor for RNA polymerase II (ELL), Myotubularin Related Protein 9 (MTMR9), leucine-rich repeat containing 25 (LRRC25), and single-stranded-DNA-binding protein 4 (SSBP4), among 26 genes." (PMID 37511476, 2023).
schizophrenia (1 paper, 2008). A major psychotic disorder characterized by abnormalities in the perception or expression of reality. "Consistent with previous studies 3 genes, MTMR9, EWSR1 and NFκβα were altered in the same direction in the post-mortem STG tissue and the peripheral blood lymphocytes (PBLs) from a separate cohort of individuals with schizophrenia identified in a previous study." (PMID 18445270, 2008).
triple-negative breast carcinoma (1 paper, 2024). An invasive breast carcinoma which is negative for expression of estrogen receptor (ER), progesterone receptor (PR), and human epidermal growth factor receptor 2 (HER2). "According to the qRT−PCR results, the mRNA expression of MTMR9 and CPNE3 was greater in triple-negative breast cancer (TNBC) cell lines (MDA-MB-231 and BT549) and ER-, PR-, and HER2+ BRCA cell line (SUM149PT)." (PMID 39524444, 2024).
cancer (2 papers, 2016 to 2019). A tumor composed of atypical neoplastic, often pleomorphic cells that invade other tissues. "The overall alteration rate of MTMR7 and MTMR9 genes was <10% in 86 cancer studies from >15 different tumor entities, indicating that the two genes are of importance beyond CRC." (PMID 27409167, 2016). "Mining of the human cancer cell line encyclopedia (CCLE) data base evinced alterations of MTMR7 in 11% and of MTMR9 in 16% of cell lines (n=1019) (data not shown)." (PMID 27409167, 2016).
tumor (2 papers, 2016 to 2024). "For example, the effects of different mutation types on MTMR9 and CPNE3 expression levels can be analyzed to understand how these mutations drive disease progression in the tumor microenvironment." (PMID 39524444, 2024). "Moreover, niclosamide can inhibit tumor proliferation and affect the expression of the target gene MTMR9, which further reflects the correlation between MTMR9 and the occurrence and development of BRCA." (PMID 39524444, 2024). "IHC demonstrated the upregulation of ACSF2, MTMR9, and CPNE3 in BRCA tissues, whereas ACSL1 expression was not significantly different between tumor tissues and adjacent tissues." (PMID 39524444, 2024).
MTMR9 also shares sentences with these, for which no sentence is quoted: type 2 diabetes (2 papers); diabetes (1); Lupus (1); Myotubular myopathy (1); osteosarcoma (1); renal carcinoma (1).